MCL1 (MCL1 apoptosis regulator, BCL2 family member)
Diseases named in the same sentence as MCL1 in open-access papers (continued):
Sharing a sentence is not in itself a finding about the gene and the disease.
cervical carcinoma (continued). "To investigate if targeting USP13 to reduce Mcl-1 expression has therapeutic potential in cervical cancer, we first assessed the impact of USP13 inhibition by the small molecule inhibitor Spautin-1." (PMID 33627786, 2021). "To confirm the clinical relevance of the USP13 – Mcl-1 interaction, we first analysed the expression of Mcl-1 in our panel of cervical cancer cells." (PMID 33627786, 2021). "Immunoprecipitation with either antibody resulted in the detection of both USP13 and Mcl-1, suggesting that the endogenous proteins interact in cervical cancer cells." (PMID 33627786, 2021). "We also demonstrate that pharmacological inhibition of USP13 sensitises cervical cancer cells to a BH3 mimetic inhibitor by reducing Mcl-1 protein expression, inducing cell death." (PMID 33627786, 2021). "In contrast, we have taken a more holistic approach and assessed the role of USP13 in Mcl-1 stabilisation with a range of complementary assays, providing robust evidence that USP13 can indeed regulate Mcl-1 expression in cervical cancer cells." (PMID 33627786, 2021). "Collectively, these findings demonstrate that USP13 and Mcl-1 are concomitantly over expressed in cervical cancer tissue, suggesting that the regulation of Mcl-1 by USP13 is clinically relevant." (PMID 33627786, 2021). "MCL-1 was found to be overexpressed in cervical cancer tissues compared to its normal counterpart and the overexpression was correlated with poor prognosis." (PMID 29580266, 2018). "There are number of studies which report that BCL-2 anti-apoptotic proteins (e.g. BCL-2, BCL-XL, and MCL-1) are highly expressed in cervical cancer tissues compared to the normal cervical epithelia." (PMID 29580266, 2018). "In our preliminary study, we aim to investigate the sensitivity of cervical cancer cell lines to ABT-263 when combined with MCL-1 selective inhibitor A-1210477." (PMID 29580266, 2018). "Down-regulation of miR-320 associated with cancer progression and cell apoptosis via targeting Mcl-1 in cervical cancer." (PMID 32309578, 2016). "Of note, we elucidated the underlying mechanisms by which taxol attenuates the migration and invasion of cervical cancer cells, possibly by activate the miR-107 and reducing the level of MCL1 expression, as well as having an anti-metastatic potential." (PMID 25386925, 2014). "Elucidation of this discovered MCL1 was directly regulated by miR-107 will greatly enhance our understanding of the mechanisms responsible for cervical cancer and will provide an additional arm for the development of anticancer therapies." (PMID 25386925, 2014). "We identified MCL1 as a target gene of miR-107, and found that miR-107 is down-regulated, whereas MCL1 is up-regulated in cervical cancer tissues when compared with adjacent normal tissues." (PMID 25386925, 2014). "Knockdown of MCL1 suppressed the growth and invasiveness of human cervical cancer HeLa and SiHa cells." (PMID 25386925, 2014). "Particularly, understanding the control of MCL1 is critical for the discovery and development of novel therapeutic agents for the treatment of cervical cancer." (PMID 25386925, 2014). "The results indicate that taxol inhibited both the activity and expression of MCL1 in cervical cancer cells." (PMID 25386925, 2014). "Compared to the control group in both two cervical cancer lines tested, taxol inhibited the protein expression of MCL1 in a dose dependent manner." (PMID 25386925, 2014). "We also demonstrated that taxol attenuated migration and invasion in cervical cancer cells by activating the miR-107, in which miR-107 play an important role in regulating the expression of MCL1." (PMID 25386925, 2014). "In this setting, we utilized an immunohistochemistry assay to further detect the MCL1 expression level in human cervical cancer tissues and adjacent normal tissues." (PMID 25386925, 2014). "Inhibition of MCL1 expression decreased viability and colony formation of cervical cancer cells when compared with control cells." (PMID 25386925, 2014).
cervical carcinoma (continued). "Together, miR-107 is a new regulator of MCL1, and both miR-107 and MCL1 play important roles in the pathogenesis of cervical cancer." (PMID 25386925, 2014). "Western blot analysis was performed to examine the protein expression of MCL1 in cervical cancer cells." (PMID 25386925, 2014). "In this study, we investigated the role of miR-107 in cervical cancer and regulates proliferation and metastasis and invasion in cells by targeting MCL1." (PMID 25386925, 2014). "Immunohistochemistry was carried out to detect the expression of p-Stat3 (Ser727), Bcl-xL, survivin, and Mcl-1 in both endometrial and cervical cancer tissues." (PMID 17311011, 2007). "Two other deubiquitinating enzyme, OTUD1 and JOSD1, have also been shown to regulate Mcl-1 in cervical cancer, suggesting that the regulation of Mcl-1 ubiquitination may be essential for cervical cancer progression." (PMID 40011575, 2025). "Furthermore, Mcl-1 has also been shown to be highly expressed in cervical cancer and correlates with proliferation and cell survival." (PMID 33627786, 2021). "Taken together, these data suggest that USP13 mediated stabilisation of Mcl-1 may be a potential mechanism for the resistance of cervical cancer cells to BH3 mimetics." (PMID 33627786, 2021). "Finally, we confirmed that depletion of USP13 from both HeLa and SiHa cells increased the ubiquitination of endogenous Mcl-1, suggesting USP13-mediated deubiquitination of Mcl-1 is relevant in cervical cancer cells." (PMID 33627786, 2021). "Interestingly, restoration of Mcl-1 expression only partially restored cell proliferation in USP13 depleted cervical cancer cells." (PMID 33627786, 2021). "As BCL-2 family members have been reported to be highly expressed in cervical cancer, BH3 mimetics may have therapeutic potential in these cancers and the high expression of Mcl-1 has been implicated as a resistance mechanism to these inhibitors." (PMID 33627786, 2021). "Importantly, expression of Mcl-1 significantly correlated with USP13 expression in cervical cancer tissue from the same patient (R = 0.4128, p = 0.009)." (PMID 33627786, 2021). "Interestingly, IL-6 also enhances cervical cancer cell survival by upregulating the anti-apoptotic protein Mcl-1, which is mediated through the activation of the PI3K/Akt pathway." (PMID 31470515, 2019). "Although the miR-107 is considered to play a key role in determining tumor properties, the regulation of MCL1 expression in cervical cancers remains largely unknown." (PMID 25386925, 2014). "Moreover, we found that MCL1 was frequently up-regulated in cervical cancer, and knockdown of MCL1 markedly inhibited cancer cell proliferation, migration and invasion, whereas ectopic expression of MCL1 significantly enhances these properties." (PMID 25386925, 2014). "This prompted us to further analyze the relevance of MCL1 for cervical cancer." (PMID 25386925, 2014). "Our results indicated that MCL1 may function as an oncogene and is a mediator of miR-107 in cervical cancer." (PMID 25386925, 2014). "Therefore, we determined by qRT-PCR that MCL1 was overexpressed in cervical cancer relative to adjacent normal tissues, and MCL1 was identified as a direct target of miR-107." (PMID 25386925, 2014). "A new target gene of miR-107, MCL1, was found to be up-regulated in cervical cancer tissues." (PMID 25386925, 2014). "Our results demonstrated that MCL1 was directly regulated by miR-107 and, moreover, suggested that miR-107 may be a potential anti-cancer therapeutic for cervical cancer." (PMID 25386925, 2014).
cervical carcinoma (continued). "Mcl-1 is a pro-survival protein that is often associated with resistance to BH3 mimetic treatment; this study demonstrated that the depletion or inhibition of USP13 sensitises HPV+ cervical cancer cells to BH3-mimetics, a potential therapeutic approach in these cancers." (PMID 40011575, 2025). "Therefore, we suggest that targeting USP13 may offer a therapeutic benefit in cervical cancer patients via the reduction in Mcl-1 protein expression." (PMID 33627786, 2021). "Importantly, the expression of USP13 and Mcl-1 proteins correlated in cervical cancer tissue." (PMID 33627786, 2021). "Our study demonstrated that co-inhibition of MCL-1 and BCL-XL was crucial for killing cervical cancer cell lines." (PMID 35201512, 2022). "Thus, we hypothesis that miR-320a/MCL1 may mediate DDP resistance in cervical cancer." (PMID 35444548, 2022). "Furthermore, whilst our data demonstrates that USP13 plays a role in regulating cervical cancer cell proliferation via the stabilisation of Mcl-1, it is clear that several other DUBs play complimentary roles in regulating Mcl-1 expression that may also play pro-oncogenic roles in cervical cancer." (PMID 33627786, 2021). "Our data demonstrate that inhibition of USP13 with Spautin-1 reduces Mcl-1 expression and sensitises cervical cancer cells to the BH3 mimetic ABT-263, offering a potential therapeutic strategy for cervical cancer." (PMID 33627786, 2021). "Our study provided new evidence that HSP90 promotes EMT through increasing the expression of Twist1 and MCL-1, which were demonstrated to accelerate the process of EMT and invasion of cervical cancer cells." (PMID 32151082, 2020). "Here we conducted a preliminary study to investigate the sensitivity of three cervical cancer cell lines to BH3-mimetic ABT-263 which selectively inhibits BCL-2, BCL-XL and BCL-w and A-1210477, a selective MCL-1 inhibitor." (PMID 29580266, 2018). "This pattern is highly reminiscent of the product of the immediate early gene X1 (IEX-1/IER3), which was previously reported to sequester MCL-1 in response to DNA damage, at least partially co-localizing with PML bodies in HeLa cervical carcinoma cells." (PMID 30123424, 2018). "It was shown for cervical cancer cells that miR-107 directly targeted MCL1 and activated ATR/Chk1 pathway to inhibit proliferation, migration and invasiveness of cervical cancer cells." (PMID 26033453, 2015). "Therefore, the identification of miR-107 and its target gene, MCL1, in cervical cancer may help us to understand potential molecular mechanisms of tumorigenesis and may provide new prognostic markers for the management of cervical cancer." (PMID 25386925, 2014). "Here we showed that miR-107 directly targeted MCL1 and activated ATR/Chk1 pathway to inhibit proliferation, migration and invasiveness of cervical cancer cells." (PMID 25386925, 2014). "Research has shown that there is overexpression of MCL1 in cervical cancer, while adjacent normal tissue showed slight or no expression of this protein." (PMID 38972247, 2024). "We assessed Mcl-1 expression in cervical cancer tissue by immunohistochemistry and observed higher expression of Mcl-1 in cervical cancer tissue when compared to non-cancer tissue." (PMID 33627786, 2021). "Mcl-1 protein levels were significantly higher in cervical cancer cells when compared to NHKs and correlated with increased USP13 expression in the cervical cancer cell lines (R = 0.862, p = 0.015)." (PMID 33627786, 2021). "New studies suggest the use of multiple biomarkers in cervical cancer management (importin-β, exportin-5, p16, Mcl1, PDL1, and cFLIP) that are not available in Romania." (PMID 30650666, 2019). "Specifically, it is well known that NF-kB regulates Mcl-1 and IL-6 expression, and these two proteins are also highly expressed in invasive cervical cancer, but not in normal cervical tissues." (PMID 31470515, 2019).
cervical carcinoma (continued). "Hence, the aim of this pilot study is to investigate the sensitivity of cervical cancer cell lines to combination of two BH3-mimetics namely ABT-263 which selectively inhibits BCL-2, BCL-XL and BCL-w and A-1210477, a selective MCL-1 inhibitor." (PMID 29580266, 2018). "MCL-1 splicing is partially regulated by SF3B1, and inhibition of SF3B1 reversed the dominant splice isoform from anti-apoptotic MCL-1L to pro-apoptotic MCL-1S in NSCLC and cervical carcinoma cell models." (PMID 27613060, 2016). "Furthermore, we report that TMS-TMF-4f could inhibit the induction of proliferative mediators such as Mcl-1, cyclin D1, survivin, and c-Myc via STAT3 inactivation, subsequently inducing apoptotic cell death in human cervical cancer cells." (PMID 31816985, 2019). "Due to activation of STAT3 and the over-induction of antiapoptotic genes found on cervical cancer cell lines after PRL stimulation, we decided to inhibit the STAT3 activation using the inhibitor AG490; which resulted in an impaired induction of Bcl-xl, Bcl-2, survivin and Mcl-1." (PMID 26346346, 2015). "Interestingly, expression of some of these genes such as Bcl-xl, survivin and Mcl-1 have been shown a strong correlation with pSTAT3 levels in cervical lesion and their expression was found abrogated by specific targeting of STAT3 in cervical cancer cells." (PMID 23874455, 2013).
cholangiocarcinoma (42 papers, 2006 to 2025). A carcinoma that arises from the intrahepatic biliary tree (intrahepatic cholangiocarcinoma) or from the junction, or adjacent to the junction, of the right and left hepatic ducts (hilar cholangiocarcinoma). "The results showed that FGFR inhibitors caused Mcl-1 expression inhibition in cholangiocarcinoma cell-matrix in the PDX model, leading to cell apoptosis." (PMID 34367944, 2021). "Further, decreased phosphatase SPH2 activity in cholangiocarcinoma patients can induce chemotherapy resistance through the MCL1-mediated pathway." (PMID 36033517, 2022). "Bcl-2 family (Bcl-xL, Bcl-2, Mcl-1) are vital members of anti-apoptotic proteins that regulate of the apoptotic pathway, and they have been reported to over-express in cholangiocarcinoma." (PMID 31391034, 2019). "Previous studies have shown that IL-6-induced Stat3 signaling upregulates Mcl-1 transcription in cholangiocarcinoma cells." (PMID 29899555, 2018). "miR-29 has been previously reported to induce cellular cytotoxicity/apoptosis by targeting anti-apoptotic protein Mcl-1 in cholangiocarcinoma." (PMID 27626694, 2016). "For instance, miR-320 was reported downregulated in malignant cholangiocarcinoma, which subsequently was found to negatively regulate Mcl-1 or Bcl-2 (anti-apoptotic molecules) expression; in turn associated with chemotherapeutic drug-triggered apoptosis." (PMID 27119506, 2016). "In conclusion, autocrine and paracrine LIF signaling promote chemoresistance in cholangiocarcinoma by up-regulating Mcl-1 via a novel STAT3- and MAPK-independent, PI3K/AKT-dependent pathway." (PMID 26296968, 2015). "Our result shows that triptolide decreases Mcl-1 expression, suggesting that triptolide sensitizes cholangiocarcinoma cells to TRAIL partially through Mcl-1 inhibition." (PMID 24742042, 2014). "Mcl-1 is an antiapoptotic member of Bcl-2 family, and induction of miR-320 activity leads to apoptosis through Mcl-1 suppression, sensitizing cholangiocarcinoma cells to 5-FU." (PMID 25250326, 2014). "Previous studies have demonstrated that miR-29a/29b can promote apoptosis by targeting MCL1 mRNA in cholangiocarcinoma cell lines." (PMID 24155920, 2013). "IL-6, which has been shown to activate Mcl-1 transcription in PCa and cholangiocarcinoma cells through a signal transducer and activator of transcription 3 (Stat3)-dependent mechanism, was included as the positive control." (PMID 22276222, 2012). "Cholangiocarcinoma cells express robust amounts of antiapoptotic Bcl-2 family proteins, in particular Mcl-1, which mitigates TRAIL cytotoxicity, consistent with a mitochondria-dependent, Type II death receptor signal." (PMID 21483830, 2011). "Mcl-1 inhibition of the mitochondrial pathway of cell death is especially relevant to cholangiocarcinoma cells as they paradoxically express TRAIL in vivo, and likely must continuously circumvent TRAIL cytotoxic signaling for survival." (PMID 21483830, 2011). "In human cholangiocarcinoma, sustained IL-6/Stat3 signalling, enhanced Mcl-1 expression and resistance to apoptosis, is attributed to epigenetic silencing of SOCS3 by promoter hypermethylation." (PMID 19698101, 2009). "Enforced miR-29b expression reduced Mcl1 protein expression in the KMCH cholangiocarcinoma cells, thus miR-29 was an endogenous regulator of Mcl1 protein expression." (PMID 17894887, 2007). "Mcl-1 downregulation has already been shown to sensitize cholangiocarcinoma cells to TRAIL-induced apoptosis and CML cells towards treatment with imatinib." (PMID 17014711, 2006). "Recently, THZ1 was shown to significantly inhibit MCL1 transcription in cholangiocarcinoma cells." (PMID 32174795, 2020). "A down-regulation of miR-29, which is expressed at high levels in primary cholangiocytes, has been shown to promote carcinogenesis in immortalized, but non-malignant (H69 cholangiocyte) as well as in malignant (KMCH) cholangiocarcinoma cell lines via regulating Mcl-1 expression." (PMID 30653586, 2019).
cholangiocarcinoma (continued). "Furthermore, forced miR-29b expression has been shown to abrogate myeloid cell leukemia-1 (MCL1) protein expression in human cholangiocarcinoma cells." (PMID 26155940, 2015). "Interleukin 6 (IL-6)-mediated signal transducers and activators of transcription 3 (STAT-3) phosphorylation (activation) is aberrantly sustained in cholangiocarcinoma cells resulting in enhanced myeloid cell leukemia 1 (Mcl-1) expression and resistance to apoptosis." (PMID 25344679, 2014). "Interestingly, Mcl-1 was found to mediate TRAIL resistance in cholangiocarcinoma cells by blocking the intrinsic pathway of apoptotic cell death." (PMID 18154639, 2007). "In cholangiocarcinoma patients, ABC294640 induces Noxa expression and Mcl-1 degradation, while Noxa knockdown prevents Mcl-1 degradation and apoptosis." (PMID 40841912, 2025). "Studies have found that the IL-6/AKT signaling pathway promotes Mcl-1 expression in cholangiocarcinoma, which in turn mediates tumor necrosis factor-related apoptosis-inducing ligand (TRAIL) resistance in cholangiocarcinoma patients." (PMID 37415745, 2023). "Interrogation of the TCGA datasets using cBioPortal indicated that MCL1, SRC and CFL1 are expressed among cholangiocarcinomas and PDACs to a similar extent to that of invasive breast carcinomas." (PMID 31735913, 2020). "In cholangiocarcinoma, pharmacological inhibition of PLK2 via BI6727 and PLK2 knockdown degrade the anti-apoptotic protein myeloid cell leukemia 1 (Mcl-1) which represents a survival factor in this malignancy, and lead to apoptosis and tumor suppression in vivo." (PMID 34065956, 2021). "A similar benefit could be possible for patients with cancers dependent on MCL-1 and SFK activity via Cofilin e.g. cholangiocarcinomas, but this remains to be investigated." (PMID 31735913, 2020). "Altough human cholangiocarcinoma do not express the protooncogene Bcl-2, other antiapoptotic proteins of the Bcl family such as Mcl-1 and Bcl-xl are expressed." (PMID 18154639, 2007). "The first miRNA targeting MCL1, miR-29, was identified in 2007 and shown to directly and negatively regulate MCL1 expression through its 3′ UTR and control apoptosis in non-malignant H69 cholangiocytes and malignant KMCH cholangiocarcinoma cell lines." (PMID 29361709, 2018). "In cholangiocarcinoma cells, we tested LIF effects on proliferation, invasion, stem cell-like phenotype, chemotherapy-induced apoptosis (gemcitabine+cisplatin), expression levels of pro-apoptotic (Bax) and anti-apoptotic (Mcl-1) proteins, with/without PI3K inhibition, and of pSTAT3, pERK1/2, pAKT." (PMID 26296968, 2015).